VCAM1 (vascular cell adhesion molecule 1)
Diseases named in the same sentence as VCAM1 in open-access papers (continued):
Sharing a sentence is not in itself a finding about the gene and the disease.
COVID-19 (continued). "We incubated HLMVEC for 24 hr with 30% patient plasma obtained from severe COVID-19 patients who were admitted to the ICU and analyzed the cells for the expression of E-selectin, VCAM-1, ICAM-1, and IL-6." (PMID 35837388, 2022). "The protein expression of E-selectin, VCAM-1 and ICAM-1 was also unaltered in samples incubated with COVID-19 patient plasma compared to mock." (PMID 35837388, 2022). "At 10 months after acute COVID-19, poor sleepers similarly showed higher levels of VCAM-1 and IL-10 on T1 blood samples, but higher VCAM-1 and IL-8 levels on T2 blood samples." (PMID 36062000, 2022). "In the current study, COVID-19 patients had higher levels of ICAM-1 and VCAM-1 than healthy control and the severe group had higher levels than the mild or moderate group, which was consistent with earlier findings." (PMID 35958594, 2022). "The findings showed that compared to healthy controls, patients with COVID-19 had significantly higher levels of interleukins 1α, 2, 6, 7, 8, 10 and 15, CRP, SAA, ICAM-1, VCAM-1, CXCL10, CCL3, CCL26, IFN-γ, TNF-α, bFGF, PlGF, and Flt-1." (PMID 35958594, 2022). "The plasma levels of VCAM-1, ICAM-1 and IL-8 were also higher in the COVID-19 patients than in the healthy control at every measurement point." (PMID 35784283, 2022). "Moreover, the expression level of several stroke-associated inflammatory genes, such as VCAM-1, SMAHD-1, and DDAH1, were significantly upregulated in COVID-19 positive patients, indicating that the inflammatory response may play potential roles in mediating COVID-19-associated stroke." (PMID 33732102, 2021). "Here, we demonstrate that the expression of KLF2 was reduced and monocyte adhesion was increased in endothelial cells treated with COVID-19 patient serum due to elevated levels of pro-adhesive molecules, ICAM1 and VCAM1." (PMID 34253708, 2021). "Biological analysis revealed significant associations between certain PACS symptoms and biomarkers of viral activation (IFNγ, IP-10), COVID-19 severity (CD163) and vascular activation (VCAM-1, ICAM-1), mainly in subjects whose symptoms had lasted less than a year." (PMID 40449327, 2025). "Others, however, suggest that a year after discharge, patients who had contracted COVID-19 did not exhibit significant differences in serum IL-6, VCAM-1, ICAM-1 or P-selectin in comparison with matched sedentary healthy controls." (PMID 38600563, 2024). "In our current study, serum VCAM-1 showed a significant elevation in both survivors and non-survivors vs. controls and effectively distinguished these two COVID-19 subgroups from each other." (PMID 38276214, 2024). "In summary, enhanced baseline levels of VCAM-1 and ACE2 can help to identify those severe COVID-19 patients who may subsequently die in ICUs." (PMID 38276214, 2024). "Vascular biomarkers VCAM-1 and Ang-2/Ang-1 ratio were predictors of death in patients with severe COVID-19 and comorbid DM and those without DM." (PMID 37585916, 2023). "Another study reported that VCAM-1 levels were higher in patients with COVID-19 and moderate-to-severe respiratory failure who did not survive." (PMID 37585916, 2023). "Furthermore, the concentration of endothelial cell adhesion molecules (such as vascular cell adhesion molecule-1 (VCAM-1) and intercellular adhesion molecule-1 (ICAM-1) is elevated in patients with COVID-19 and contributes to coagulation dysfunction." (PMID 37896963, 2023). "In severe COVID-19 patients admitted to ICU (n = 38), increased levels of ICAM-1 and E-selectin, but not VCAM-1 or P-selectin, were found in COVID-19 patients who died during hospitalization (n = 10), compared to survivors (n = 28)." (PMID 36941580, 2023). "Compared to the healthy controls, patients with COVID-19 had significantly higher circulating concentrations of 19 inflammatory mediators, namely interleukins 1α, 2, 6, 7, 8, 10 and 15, CRP, SAA, ICAM-1, VCAM-1, CXCL10, CCL3, CCL26, IFN-γ, TNF-α, bFGF, PlGF and Flt-1 (P < 0.05)." (PMID 35958594, 2022).
COVID-19 (continued). "Moreover, in severe COVID-19 patients the plasma levels of adhesion molecules such as intercellular adhesion molecule 1 (I-CAM-1), vascular cell adhesion molecule-1 (VCAM-1), vascular adhesion protein-1 (VAP-1), were reported to be elevated." (PMID 35601094, 2022). "In addition, endothelial activation markers, including soluble VCAM-1 (sVCAM-1), soluble TNF receptor I (sTNFRI), and heparan sulfate, were increased in patients with COVID-19, and the increased expression was related to COVID-19 disease severity." (PMID 36013974, 2022). "In severe COVID-19 patients, the plasma levels intercellular adhesion molecule 1 (I-CAM-1), vascular cell adhesion molecule-1 (VCAM-1), and vascular adhesion protein-1 (VAP-1), are elevated, indicating that the endothelial barrier is damaged consecutive to viral infection." (PMID 36519165, 2022). "Endothelial cell activation markers were similarly distributed with the exception of higher VCAM-1 levels in COVID-19 males vs. females (data not shown)." (PMID 36203596, 2022). "Among elevated plasma inflammatory mediator levels; CRP, ICAM-1, SAA, VCAM-1, CXCL10, IL-7, IL-10 and Flt-1 may suggest the severity of COVID-19." (PMID 35958594, 2022). "We found that Ang-2 (AUROC 0.75, best cutoff > 2800 pg-mL), RAGE (AUROC 0.69, best cutoff < 208 pg/mL), VCAM-1 (AUROC 0.74, best cutoff > 1312 ng/mL) and ICAM-1 (AUROC 0.63, best cutoff > 1092 ng/mL) were able to discriminate between COVID-19 and classical ARDS." (PMID 33608030, 2021). "Endothelial activation was absent in renal tissue from COVID-19 patients as indicated by the lack of E-selectin, VCAM-1 and ICAM-1 upregulation." (PMID 34112226, 2021). "Furthermore, IGFBP-1, IL-16, macrophage colony-stimulating factor (M-CSF), and VCAM-1 positively correlated with SOFA- and WHO scores, representing the contribution of the endothelium to severe COVID-19." (PMID 34893580, 2021). "Although VCAM1 levels were gradually increased in all COVID-19 cases compared with controls, it was not statistically significant." (PMID 34836309, 2021). "Finally, a total of eleven differential factors related to COVID-19 disease severity were identified, including: TRAIL R1, IGFBP-1, IGFBP-4, VCAM-1, sFRP-3, FABP2, Transferrin, GDF15, IL-1F7 (also known as IL-37), IL-5Rα, and CD200." (PMID 34335566, 2021). "Second, we were unable to measure VCAM-1 expression in the tissues, even though no study to date dealing with COVID-19 was able to assess such data." (PMID 34422854, 2021). "Additionally, we observed a reduction of s-VCAM-1 in all patient groups throughout hospitalization, which is in accordance with findings of comparable VCAM-1 concentrations in long COVID-19 patients and controls if we assume that VCAM-1 returns to normal in some months." (PMID 39862311, 2025). "A recent study demonstrated that patients with COVID-19 have higher levels of VCAM-1 than controls with the same clinical presentation but without SARS-CoV-2 infection, supporting the concept that COVID-19-associated pneumonia specifically affects the endothelium." (PMID 37585916, 2023). "So, on a speculative plan, it is possible that the post-acute overexpression of VCAM-1 and IL-8 in poor sleepers could be somehow influenced by higher levels of pro-inflammatory cytokines (including IL-1 and TNF-α) during the acute phase of COVID-19." (PMID 36062000, 2022). "Notably, the plasma levels of adhesion molecules, such as ICAM-1, fractalkine, vascular cell adhesion molecule-1 (VCAM-1), vascular adhesion protein-1 (VAP-1), and vascular endothelial growth factor (VEGF), have been reported to be elevated among COVID-19 patients, especially in severe cases." (PMID 34578436, 2021). "Serum levels of VCAM-1 were found to be higher in COVID-19 patients than in non-COVID-19 patients." (PMID 34836309, 2021).
COVID-19 (continued). "Previous studies suggested that VCAM-1, and intracellular cell adhesion molecule-1 (ICAM-1) might promote the interaction between leukocytes and endothelial cells, by serving as ligands for integrins, and thus may play an important role in COVID-19 pathogenesis." (PMID 35836945, 2022). "Our findings reveal that CRP, SAA, VCAM-1, CXCL10, CCL22 and IL-10 levels are promising biomarkers for COVID-19 disease severity, suggesting that plasma inflammatory mediators could be used as warning indicators of COVID-19 severity, aid in COVID-19 prognosis and treatment." (PMID 35958594, 2022). "Adhesion molecules such as E-selectin, VCAM1 and ICAM1 are known to promote monocyte adhesion via integrin interaction, whereas an elevated PAI-1 level promotes thrombosis by inhibiting tPA, all of which may contribute to pro-inflammatory and pro-thrombotic conditions in patients with COVID-19." (PMID 34835015, 2021). "Indeed, plasmatic level of vascular cell adhesion molecule-1 (VCAM-1), intercellular adhesion molecule 1 (ICAM-1), plasminogen activator inhibitor-1 (PAI-1), tissue factor (TF), and von Willebrand factor (vWF) antigens and activities are all elevated in severe COVID-19 cases." (PMID 35111777, 2021). "A prior study has reported increased levels of circulating E-selectin and VCAM-1 in ICU, as compared to non-ICU COVID-19 patients." (PMID 34835015, 2021). "When comparing only patient groups in the first week of hospitalization, s-ICAM-1 and s-VCAM-1 values did not significantly differ between patient groups, although s-VCAM-1 values tended to be lower in patients with critical COVID-19 on VV-ECMO (P = 0.053 vs. severe, at admission)." (PMID 39862311, 2025). "The aim of this study was to evaluate whether the plasma levels of “endothelial” and “alveolar” biomarkers (Ang-2, ICAM-1, VCAM-1, P selectin, E-selectin and RAGE) vary over time between survivors and non-survivors in COVID-19-related ARDS patients." (PMID 33608030, 2021).
Stroke (78 papers, 2009 to 2026). Sudden impairment of blood flow to a part of the brain due to occlusion or rupture of an artery to the brain. "It has been reported that the improvement in stroke severity is associated with neuroplasticity, which, in turn, relates to VCAM-1, MMP-9, S100β, and vWF." (PMID 39599732, 2024). "For example, the increase in the adhesion molecule VCAM-1 was associated with lower flow-mediated vasodilation in stroke patients." (PMID 39311310, 2024). "We have also identified haplotypes of VCAM1 promoter variants as well as a specific variant (rs1409419_T) with a strong association, not only with stroke, but also with hemolysis." (PMID 38001830, 2023). "VCAM‐1 levels increase from the onset to the chronic phase of stroke, and soluble VCAM‐1 levels are associated with short‐term mortality as non‐survivors have higher levels than survivors." (PMID 37452512, 2023). "VCAM-1 is an early marker of unstable atherosclerotic plaques and OxLDL is significantly associated with cardiovascular events and stroke in humans." (PMID 26938557, 2016). "Such high levels of E-selectin and VCAM-1 have been described as decreasing within the first 4 days after stroke onset, in association with the clinical improvements seen in patients." (PMID 26543408, 2015). "With respect to mechanism underlying reduced stroke volume in iBEC-G153-KO, histological analyses showed reduced VCAM1 expression in the infarct periphery in iBEC-G153-KOs, and the number of neutrophils that had extravasated into the brain parenchyma was reduced." (PMID 40623996, 2025). "One stroke-associated gene, VCAM-1, connects the viral entry process, dysregulation of the RAAS and immune response, vessel endothelial cell damage, and clotting cascade together, indicating that we should recognize SARS-CoV-2 infection from a holistic perspective, rather than independent mechanism." (PMID 33732102, 2021). "Furthermore, VCAM1 has also been found to be associated with impaired endothelial dependent dilation in cerebral artery vasoreactivity, early after stroke with poor prognoses." (PMID 32508734, 2020). "Several groups have shown improved stroke outcomes in association with decreased VCAM-1 expression." (PMID 31281252, 2019). "Moreover, VCAM-1 is suspected to mediate inflammation in atherosclerotic plaques, increasing the risk of rupture and a recurrence of vascular events in stroke patients." (PMID 26543408, 2015). "Increased VCAM‐1 concentrations correspond to larger infarct volumes and a 30% higher likelihood of recurrent stroke." (PMID 41567175, 2026). "Since the expression of VCAM-1 was increased in CECs after stroke, a VCAM-1-based RNA aptamer was recently obtained, and an effective aptamer-based delivery platform to target CECs was constructed to treat cerebral ischemia." (PMID 40376266, 2025). "Elevated levels of ICAM-1 and VCAM-1 have been detected in the blood and infarct regions of stroke patients." (PMID 40066310, 2025). "The use of Notch1 or VCAM1 blocking antibodies as well as the knockdown of endothelial Notch1 both reduced atherosclerosis progression after stroke." (PMID 40565303, 2025). "In the pathological process of stroke, IL-11 can upregulate the expression of vascular cell adhesion molecule-1 (VCAM-1) through its proinflammatory effects, leading to vascular inflammation and injury." (PMID 39787159, 2025). "In the chronic phase of stroke, we observed that as venous ECs gradually regenerate, the expression of VCAM‐1 is further upregulated, promoting the infiltration of lymphocytes, particularly T cells." (PMID 40421577, 2025).
Stroke (continued). "It has been shown that cerebral ischemia induces the sustained activation of peripheral EC, the upregulation of the adhesion molecule VCAM1, and increased senescence, and these changes persist up to 4 weeks after stroke." (PMID 40565303, 2025). "The serum levels of VCAM-1 reflect changes in the brain and correlate with brain infarct volume and brain edema volume, which affect the reduction of stroke severity." (PMID 39599732, 2024). "To test if this VCAM-1-aptamer affects stroke outcomes, we performed tMCAO in a separate cohort of mice and injected VCAM-1-aptamer (0.5 nmol) compared to PBS control." (PMID 37339993, 2023). "Confocal microscopy further confirmed that Cy5 fluorescence overlapped with CD31 + CECs in VCAM-1-aptamer treated stroke mice." (PMID 37339993, 2023). "Herein, we report that an RNA-based VCAM-1-aptamer can specifically target CECs in stroke brains following transient middle cerebral artery occlusion in mice." (PMID 37339993, 2023). "Quantified relative expression of Cy5 in CD31+ CECs demonstrated that the MFI of Cy5 was significantly higher in stroke brains of VCAM-1-aptamer treated stroke mice." (PMID 37339993, 2023). "For example, patients with a high risk for stroke occurrence have hypomethylated Long Interspersed Nucleotide Element-1 (LINE-1) repeats, associated with increased circulating vascular cell adhesion molecule-1 (VCAM-1) levels." (PMID 36855111, 2023). "The goal of this study is to test the ability of this RNA-based VCAM-1-aptamer to target CECs in vivo after stroke as well as evaluate effectiveness for treating ischemic stroke using a murine transient middle cerebral artery occlusion (tMCAO) model." (PMID 37339993, 2023). "A metanalysis based on 4816 patients affected by ischemic strokes, reported higher levels of ED markers than non-stroke individuals (E-Selectin, P-Selectin, intercellular cell adhesion molecule, and vascular cell adhesion molecule 1 VCAM-1)." (PMID 35055099, 2022). "A longitudinal prospective study on soluble adhesion molecules after cerebral infarction reported that soluble VCAM1 reached its maximum plasma levels at 5 days after stroke." (PMID 33971895, 2021). "Systemic VCAM1 levels were found to be significantly higher in the severe stroke quartile as compared to the mild stroke quartile (mean for mild = 5.4, SD = 0.22; mean for severe = 5.7, SD = 0.43; p value = 0.024)." (PMID 33971895, 2021). "Second, we investigated the relationships of systemic and intracranial VCAM1 with metrics of stroke severity and functional recovery including infarct volume, infarct edema, infarct time, and National Institute of Health Stroke Scale/Score (NIHSS)." (PMID 33971895, 2021). "Taken together, these studies provide insight into the timeline of VCAM1 activation/inactivation in the acute event as well as in the post-stroke recovery time and how that directly affects stroke severity and recovery." (PMID 33971895, 2021). "Secondly, the function of VCAM1 is particularly relevant to neuroinflammation in stroke as it acts to permit extravasation of leukocytes through the vascular wall into brain tissue." (PMID 33971895, 2021). "As increased VCAM1 levels were predictive of infarct volume and edema volume, future studies will aim to reverse translate these results into experimental stroke models with intention of neutralizing VCAM1 in the acute phase of ischemic stroke." (PMID 33971895, 2021). "The current study provides novel data on systemic and intracranial VCAM1 in relation to stroke comorbidities, stroke severity, functional outcomes, and the role VCAM1 plays in complex protein-protein signaling pathways." (PMID 33971895, 2021). "In patients with stroke, the concentration of VCAM-1 in blood and its expression in endothelial cells and astrocytes in the ischemic region of the brain were significantly increased." (PMID 34868060, 2021).